GDF15 (growth differentiation factor 15)
Diseases named in the same sentence as GDF15 in open-access papers (continued):
Sharing a sentence is not in itself a finding about the gene and the disease.
Obesity (continued). "One study found that CPT effectively addresses obesity in mice through induction of the GDF15–GFRAL pathway." (PMID 40837873, 2025). "Obesity is a risk factor for type 2 diabetes mellitus (T2DM), and some evidence from animal studies suggests that treatment with GDF-15 decreases body weight and glucose levels, primarily due to the loss of fat mass and reduced food intake." (PMID 40722664, 2025). "Recognizing the pivotal role of GDF-15 in metabolic disorders, it becomes imperative to explore its relationship with variables such as gender and ethnicity, particularly in regions where obesity and diabetes are prevalent." (PMID 40722664, 2025). "Our findings support that obesity, T2D, and aging increase the concentrations of both GDF15 and FGF21." (PMID 40828431, 2025). "The GDF-15 RA use as a potential treatment for obesity stems from observations that elevated tumour-secreted GDF-15 is correlated with WL." (PMID 38302593, 2025). "Adipose tissue macrophages were shown to secrete GDF-15 during the early stages of obesity and type 2 diabetes, while hepatocytes upregulated GDF-15 in the liver in during MASH." (PMID 40955668, 2025). "These anorexigenic and weight‐suppressive actions make GDF15 a very attractive molecule from a translational point of view, encouraging potential applications in the treatment of obesity, metabolic disorders, but also feeding and eating disorders." (PMID 40464681, 2025). "Another potential therapeutic pathway for obesity pharmacotherapies is through the stress-induced cytokine GDF-15, which is expressed in multiple cell types including cardiomyocytes, adipocytes and macrophages." (PMID 38302593, 2025). "Specifically in the context of obesity, GDF15 administration would be able to promote sympathetic activation and enhance thermogenesis in adipose tissues, aiding in weight management and metabolic regulation." (PMID 41034527, 2025). "Specifically, the binding of GDF-15 to hindbrain GFRAL has anti-obesity actions in mice by reducing food consumption." (PMID 39683685, 2024). "The upregulation of GDF15 in obesity appears to serve as a compensatory mechanism for impaired muscle mitochondrial function." (PMID 39700016, 2024). "By improving lipid breakdown and decreasing adipose inflammation, TFEB-induced GDF15 protects against diet-induced obesity and insulin resistance." (PMID 39000187, 2024). "A recent study showed that a long‐acting GDF15 analogue was successful in reducing food intake in rodents and in humans living with overweight and obesity." (PMID 38965822, 2024). "The effects of GDF-15 on food intake and obesity are being extensively researched, but its potential neurotrophic effects remain largely unexplored." (PMID 39683685, 2024). "GDF15 knockout mice consuming a high-fat diet have worsened glucose tolerance and metabolic rate, indicating a possible protective role of GDF15 in obesity, whereas a microarray study has shown that total GDF15 is upregulated in obese mice, rats, and humans." (PMID 38762719, 2024). "We further demonstrated that the anti-obesity effect of artesunate was mainly mediated by the GDF15/GFRAL signalling axis." (PMID 38310105, 2024). "In early stages of obesity, GDF15, produced by macrophages in adipose tissue, can reduce weight gain, although this antiobesity effect appears to diminish as obesity progresses." (PMID 39700016, 2024). "For example, the stress alarmone and anorectic protein Gdf15 interact with members of two other groups, including inflammatory Cx3cl1, axon guidance-related protein (Bmp3), and the obesity-related proteins Timp1 and erythropoietin (Epo)." (PMID 39329749, 2024). "The increased expression of GDF15 significantly alleviated the HFD-induced obesity and hepatic steatosis in transgenic mice." (PMID 39643709, 2024).
Obesity (continued). "As present research mainly focuses on the exclusive role of GFRAL in the AP/NTS in anorexia, tumor-induced cachexia and obesity, the data on potential GDF15/GFRAL signaling in other brain areas are sparse." (PMID 38474863, 2024). "In the future, additional research is necessary to investigate the impact of various forms of GDF15 on cellular inflammation development in obesity." (PMID 39700016, 2024). "While a few studies have reported an acute increase in GDF‐15 concentrations, evidence in the context of obesity remains limited." (PMID 39263536, 2024). "Although GDF15 holds great potential in the treatment of obesity and metabolic diseases, its side effects, particularly nausea, vomiting and gastrointestinal discomfort, remain major challenges in its clinical application." (PMID 39700016, 2024). "At the 8-week time point, plasma leptin and plasma GDF15 levels were reduced in Pter KO mice, a result consistent with the reduced adiposity and obesity of these animals at that time point." (PMID 39112712, 2024). "This analysis showed that some proteins, such as COL1A1, COL6A3, FABP4, LEP, LGALS1, and THBS4, are obesity-specific, and GDF15, LPL, MCFD2, REG1A, REG1B, and TCN2 are T2D-specific." (PMID 38732002, 2024). "Given the appetite-regulatory nature of GDF15, it has drawn much attention from the basic research and pharmacological sectors for its potential as an anti-obesity agent." (PMID 38310105, 2024). "In this review, we will summarise the molecular mechanisms of GDF15‐GFRAL pathway in obesity, and we will also discuss the efficacy of drugs that target the GDF15‐GFRAL pathway for the treatment of obesity and the potential challenges." (PMID 39700016, 2024). "Artesunate has a number of advantages over other GDF15 agonists, such as recombinant GDF15 proteins, in combating obesity." (PMID 38310105, 2024). "Sixty minutes of MICT increased GDF‐15 while suppressing appetite perceptions in individuals with obesity." (PMID 39263536, 2024). "This anti-obesity action of GDF-15 was abrogated in GFRAL gene-deleted mice, while diet-induced obesity was exacerbated in GFRAL-deficient mice." (PMID 38672115, 2024). "GDF15 is widely investigated in several metabolic dysfunctions, including obesity, diabetes, and fatty liver diseases." (PMID 38725041, 2024). "Although some studies have shown a relationship between GDF15 and obesity and thus proposed a role in modulating energy metabolism and homeostasis, others have casted doubts on these findings." (PMID 38762719, 2024). "The activation of TFEB-growth differentiation factor-15 (GDF15) in macrophages can regulate metabolic disorders such as obesity induced by HFD." (PMID 39758315, 2024). "One of the most interesting proteins listed in the table related to obesity and feeding behavior is Gdf15." (PMID 39329749, 2024). "Recently, a study has shown that in obesity, the accumulation of macrophages in adipose tissue triggers an elevation in GDF‐15 levels, a process that is exacerbated when coexisting with T2D." (PMID 39700016, 2024). "The transcription factor EB (TFEB)–GDF15 axis is essential in adapting to obesity-induced metabolic stress; GDF15 acts as a ‘lysokine’ released in reaction to lysosomal stress via TFEB activation." (PMID 39000187, 2024). "A limited number of studies in this area showed that 12 weeks of aerobic training at ∼ 85% maximum heart rate in older adults with obesity led to a significant increase in GDF-15." (PMID 38409184, 2024). "The most interesting finding in this study was that serum CES1 levels were significantly associated with lipid metabolism (ALT, AST, TG, TC, LDL-C), glucose metabolism (FBI, HOMA-IR) and obesity-related secreted proteins (adiponectin, leptin, GDF15, IGF-1)." (PMID 39227971, 2024). "Enhanced insulin sensitivity and protection against diet-induced obesity have been demonstrated in transgenic mice over-expressing GDF15." (PMID 39000187, 2024).
Obesity (continued). "The physiological role of GDF15 has garnered increased attention in recent years, with studies revealing its involvement in various conditions such as sepsis, obesity, cancer, and cachexia." (PMID 39766300, 2024). "Artesunate treatment induced an increase in serum GDF15 levels in mice fed the control diet; this inductive effect was further exaggerated in mice with diet-induced obesity." (PMID 38310105, 2024). "In an obesity-related disease state, higher GDF-15 concentrations and lower adiponectin levels have been observed." (PMID 37152921, 2023). "This emphasizes the differences between individuals in the physiology and secretion profiles of GDF-15 in response to the obesity intervention." (PMID 37436597, 2023). "Intensity of the morning low back pain correlated with adipsin concentration after therapy in the obesity group and with GDF-15 concentration in the normal-weight group before the intervention." (PMID 36927409, 2023). "Circulating levels of GDF15 are increased with obesity, chronic inflammation, and reduced exercise training." (PMID 36678157, 2023). "In mouse models, GDF15 acts as a regulator of obesity, decreasing glucose intolerance and increasing lipid metabolism." (PMID 37408184, 2023). "GDF-15 exerts its known anti-inflammatory properties against obesity by regulating at least in part the activation of ATMs." (PMID 37283763, 2023). "There is conclusive evidence that GDF15 is an attractive target for the treatment of obesity and T2DM." (PMID 37513338, 2023). "Overall, these findings suggest that pharmacological modulation of GDF15 shows promise for the treatment of obesity and its complications, such as type 2 diabetes mellitus (T2DM)." (PMID 37513338, 2023). "The PPT on the right side correlated negatively with a change in GDF-15 concentration in women with obesity before therapy." (PMID 36927409, 2023). "GDF15 belongs to the TGFβ family, whose function has recently gained attention due to its anti-inflammatory, antioxidant and potential anti-obesity effects." (PMID 37400902, 2023). "In COVID-19, the cytokine storm contributes to rapid deterioration in patients with pre-existing chronic inflammatory conditions such as obesity, hypertension, and diabetes, which are correlated with elevated levels of GDF15." (PMID 37408184, 2023). "In recent years, GDF15 has received increased attention due to its anti-inflammatory, antioxidant and potential anti-obesity effects." (PMID 37400902, 2023). "GDF-15 was significantly reduced in the normal-weight group, while significantly increased in the obesity group." (PMID 36927409, 2023). "The precise biological role of GDF15 remains to be elucidated, including its role in the pathophysiology of diabetes, obesity and CVD." (PMID 36992609, 2023). "GDF15 levels increase in the liver and white adipose tissues in mouse models of diet-induced obesity (DIO)." (PMID 37538245, 2023). "Several studies have shown that treatment with recombinant-GDF15 attenuates obesity and improves glycemic control through GFRAL-dependent suppression of food intake." (PMID 37818094, 2023). "Overweight/obesity, and more largely MetS, appear to be the target with the biggest potential for GDF15 treatment in humans." (PMID 36992609, 2023). "Altogether a core body of evidence suggests that GDF15 can be considered to be one of the factors controlling body weight and represents a valuable target to combat obesity." (PMID 36992609, 2023). "Growth differentiation factor 15 (GDF15), a member of the TGF-β superfamily, is associated with many biological processes such as cancer, obesity, energy homeostasis, and body weight regulation." (PMID 37207185, 2023). "Increased GDF-15 levels have been reported to be correlated with many metabolic diseases, including obesity, cardiovascular disease (CVD), type 2 diabetes mellitus (T2DM), and metabolic-associated fatty liver disease." (PMID 37152921, 2023).
Obesity (continued). "Growth differentiation factor 15 (GDF-15) has been shown to be a metabolic and appetite regulator in diabetes mellitus (DM) and obesity." (PMID 37152099, 2023). "Targeting growth differentiation factor 15 (GDF15) is a recent strategy for the treatment of obesity and type 2 diabetes mellitus (T2DM)." (PMID 37513338, 2023). "Consistent with this role of GDF15, transgenic mice overexpressing Gdf15 display a lean phenotype and a reduction in food intake and are more resistant to obesity, metabolic inflammation, and glucose intolerance." (PMID 37513338, 2023). "This heterogeneity becomes especially obvious in different types of cancer as well as obesity and cachexia, where in particular GDF15 can be either protective or detrimental." (PMID 36642986, 2023). "Conversely, as in OPA1 BKO mice, long-term induction of GDF15 attenuated progression of obesity by increasing energy expenditure in DIO, while FGF21 was dispensable for this phenotype." (PMID 37819027, 2023). "After therapy, the maximal low back pain decreased in both groups, GDF-15 concentration was reduced in the normal-weight group and increased in the obesity group, and CS-846 concentration decreased in the obesity group." (PMID 36927409, 2023). "After the therapy the correlation between intensity of low back pain while sitting and the GDF-15 concentration was found in women with obesity." (PMID 36927409, 2023). "In light of the increase in GDF15 levels in several conditions and pathologies including obesity, diabetes and exercise, numerous regulators have been identified that are involved at different stages of GDF15 production." (PMID 36992609, 2023). "Previous studies have shown that there was variability in GDF-15 response of anti-obesity treatments." (PMID 37436597, 2023). "In mice, elevated GDF-15 has shown to be protective against diet-induced obesity and insulin resistance in the context of selective muscle mitochondrial dysfunction." (PMID 37152099, 2023). "Higher expression of ANGPT2, HIF-1a, EGFL6, several MMP genes, and GDF15 was observed in individuals living with obesity (p ≤ 0.008)." (PMID 38024342, 2023). "Recent studies also uncovered roles for GDF15 in mediating the beneficial effects of compounds with anti-obesity properties, including metformin, capsaicin, resveratrol and conjugated linoleic acid." (PMID 37818094, 2023). "Here, by screening of CMAP database, we found a strong correlation between CPT and GDF15 expression, suggesting a potential anti-obesity property of CPT." (PMID 35202387, 2022). "GDF15 has been demonstrated its multiple important roles in several diseases comprising obesity, cachexia, and cardiovascular disease." (PMID 34697897, 2022). "To achieve our aims, we measured GDF15 in 175 youth with overweight/obesity who underwent an oral glucose tolerance test and an MRI to measure intrahepatic fat content." (PMID 35194014, 2022). "Together, these results indicate that CPT is a promising anti-obesity agent through activation of GDF15-GFRAL pathway." (PMID 35202387, 2022). "It is well established that both the occurrence and severity of COVID-19 increase with age, and the presence of comorbidities such as hypertension, diabetes, obesity, and cardiovascular disease conditions also largely related to the production of GDF15." (PMID 35937703, 2022). "The role of serum GDF15 has been evaluated in large patient cohorts as a biomarker for mitochondrial dysfunction, obesity, diabetes, cardiovascular diseases, ageing, and age-related disorders." (PMID 35323645, 2022). "Plasma GDF15 is elevated in a range of human diseases, in addition to obesity and the metabolic syndrome, where it is widely considered to be a useful biomarker." (PMID 36064109, 2022). "A subgroup of 22 youth with obesity who increased or decreased in HFF% by at least 30% of original over a two-year period was assessed for changes in plasma GDF15 concentrations." (PMID 35194014, 2022).
Obesity (continued). "One study found increasing GDF15 concentrations after an oral glucose tolerance test (75 g dextrose) in younger to middle-aged adults with obesity." (PMID 36235718, 2022). "Herein, we show that in youth with overweight/obesity, GDF15 plasma concentration is associated with NAFLD and NAFLD-related phenotypes and that changes in plasma GDF15 concentration are driven by changes in intrahepatic fat content." (PMID 35194014, 2022). "Both stress-induced cytokines, GDF15 and FGF21, have attracted considerable interest as potential therapies for obesity and its associated metabolic disease." (PMID 36064109, 2022). "It appears reasonable that considerable loss of weight and fat mass is accompanied by a significant reduction of elevated, obesity-related GDF15 levels." (PMID 36430499, 2022). "The independent identification by multiple laboratories of GFRAL as the neuronal receptor for GDF-15 which mediates its known anti-obesity effects has also accelerated research into GDF-15 as a weight-loss promoter." (PMID 35821815, 2022). "Here we used tissue selective knockout mouse models and human transcriptomics to determine the source of circulating GDF15 in obesity." (PMID 36064109, 2022). "As a nutrient-sensing and regulatory factor, GDF15 plays a key role in metabolic diseases, such as obesity and diabetes." (PMID 36387916, 2022). "This study reveals that the small molecule Camptothecin induces endogenous GDF15, suppressing food intake and reducing body weight in obese mice, suggesting a promising candidate for anti-obesity treatment." (PMID 35202387, 2022). "Overall, our present data confirm the potential of GDF15 as a reliable biomarker for hypertension in severe obesity." (PMID 36430499, 2022). "Experimental GDF15 injection to animal models of obesity and diabetes have reported positive results." (PMID 36046792, 2022). "GDF15 has been recently recognized as a metabolic regulator, due to its role in regulating appetite and metabolism and obesity through its receptor." (PMID 35937703, 2022). "Plasma GDF15 concentrations were measured by ELISA in 175 youth with overweight/obesity who underwent an oral glucose tolerance test (OGTT) and magnetic resonance imaging (MRI) to assess intrahepatic, visceral, and subcutaneous fat." (PMID 35194014, 2022). "Higher expression of angiopoietin-2 (ANGPT2), HIF-1α, EGF like domain multiple 6 (EGFL6), several MMP genes, and growth/differentiation factor-15 (GDF15) was observed in individuals living with obesity (P ≤ 0.008)." (PMID 35958557, 2022). "Meanwhile, the circulating GDF15 levels have been reported to be correlated with heart failure, cancer, renal dysfunction, diabetes mellitus, mitochondrial disease, and obesity." (PMID 35683420, 2022). "Overexpression of GDF15 has been noted to protect against high-fat diet-induced obesity and glucose intolerance, while GDF15-knockout mice have been reported to gain body weight and store fat, concomitant with increased food intake." (PMID 35683420, 2022). "Of particular importance, data supporting the putative role of GDF15 as an obesity-independent marker and predictor of hepatic fibrosis remain scarce so far." (PMID 36430499, 2022). "Four target areas (leptin, ghrelin, mitochondrial uncouplers and growth differentiation factor 15 (GDF15)) were initiated and advanced with obesity constituting the primary therapeutic purpose." (PMID 34815532, 2022). "GDF15 plasma levels are elevated in animal models of obesity; however, administration of recombinant protein robustly lowers body weight in obese and diabetic animals, including non-human primates." (PMID 35916366, 2022). "High GDF15 circulating levels have been observed in patients with type II diabetes mellitus or obesity related to impaired glucose control." (PMID 35160008, 2022). "Meanwhile, GDF15 over-expressing transgenic mice are protected from diet-induced obesity and display improved insulin sensitivity." (PMID 36064109, 2022).